BRAF (B-Raf proto-oncogene, serine/threonine kinase)
Diseases named in the same sentence as BRAF in open-access papers (continued):
Sharing a sentence is not in itself a finding about the gene and the disease.
cancer (continued). "Their efficacy has been curtailed by the toxicity of the side effects and development of resistance in patients as well as the emergence of secondary cancers such as cutaneous squamous cell carcinoma due to the activation of BRAF inhibitor-induced paradoxical activation of MAPK pathway." (PMID 26767073, 2016). "Serrated neoplasia may originate in sessile serrated adenomas (SSA) or traditional serrated adenomas (SSA), the former being the precursor of MSI cancers and the latter preceding the development of BRAF mutant / MSS cancers." (PMID 27661107, 2016). "However, there are both reports supporting and refuting the increase in ERK activity in cancer tissues expressing the active Ras and BRaf proteins." (PMID 27936234, 2016). "The epigenetic instability of BRAF mutant cancers in particular can induce DNA methylation and silencing of other Wnt pathway molecules that may alter the sensitivity of the cells to an upstream porcupine inhibitor." (PMID 27661107, 2016). "The novel combination of Porcupine and MEK inhibition synergistically inhibited RKO cell growth by more than 90%, which suggests this may be a promising therapeutic strategy to treat BRAF / RNF43 / ZNRF3 mutant serrated pathway cancers." (PMID 27661107, 2016). "It is shown here that by using specific autophagy inhibitors not only cancer cell proliferation rate can be reduced, but the otherwise resistant mutant BRAF colon cell lines to targeted BRAF agents, like PLX4720 (Vemurafenib), can be sensitised to apoptosis in a synergistic manner." (PMID 26802026, 2016). "In our study, we obtained sequencing data on 50 cancer‐related genes in cases of pediatric AF and compared them with findings in the adult counterpart of AF, identifying significant differences mainly involving AKT1 and BRAF mutations in pediatric AF." (PMID 27062580, 2016). "Again BRAF mutant/MSI cancers rarely showed deletion events at this locus (1/30, 3.3%)." (PMID 27661107, 2016). "Thus, whereas autophagy can protect cancer cells from cytotoxic treatments, its inhibition can improve the effects of selective BRAF inhibitors in BRAFV600E CRC cells." (PMID 26750638, 2016). "Our study suggests that PPP-subfamily phosphatases may be responsible for cell density-dependent ERK dephosphorylation in cancer cells expressing active Ras or BRaf protein." (PMID 27936234, 2016). "In patient P4, two of four malignant ascites-emerging clones may be targetable by inhibitors against BRAF (e.g. Vemurafenib), TEP1, ERBB4, PIK3CA, HDAC9, or FYN." (PMID 26811494, 2016). "Type I cancers commonly exhibit mutations in KRAS, BRAF, CTNNB1, PIK3CA, PTEN, ARID1A, or PPP2R1A." (PMID 27421040, 2016). "Cytoplasmic RNF43 expression was least frequently observed in the BRAF mutant/MSI cancers." (PMID 27661107, 2016). "BRAF wildtype cancers also showed a significant increase in level of transcript expression." (PMID 27661107, 2016). "In addition to the G659 (G7 deletion), recurrent frameshift mutations were present at R117 (C6 repeat tract) in exon 3 and affected 6/54 (11.1%) of BRAF mutant/MSI cancers." (PMID 27661107, 2016).
cancer (continued). "In addition to frequent loss of heterozygosity of ZNRF3 occurring in the BRAF mutant/MSS cohort, one of these cancers harboured a homozygous deletion spanning approximately 170kb and including the C terminal half of the ZNRF3 locus." (PMID 27661107, 2016). "Although many human cancers carry the mutated BRAF gene, this mutation has not yet been characterized in canine cancers." (PMID 26053201, 2015). "For instance, in a study involving 110 PTC patients, follow-up was relatively short (8 months) and no impact of BRAF mutation on cancer stage and prognosis was demonstrated." (PMID 26177218, 2015). "Interestingly, there was substantial loss of protein expression in both the BRAF mutant (92/97, 94.5%) and BRAF wild type (39/44, 88.6%) cancer cohorts." (PMID 25613750, 2015). "The frequency of BRAF mutation and CIMP increased from serrated polyp to cancer as expected." (PMID 25613750, 2015). "Similarly, in BRAF mutantcolorectal cancers, feedback activation of EGFR-dependent signaling attenuates theconsequences of mutant BRAF inhibition, suppressing the apoptotic effect." (PMID 25686219, 2015). "In France, the French National Cancer Institute (INCa) has set up a national network of 28 regional molecular cancer genetics platforms where selective molecular tests, including BRAF V600 genotyping, are routinely performed using methods specific to each laboratory." (PMID 25789737, 2015). "Somatic mutations in cancer driver genes, tumor suppressors, and amplified oncogenes such as EGFR, RAS, BRAF, MYC, isocitrate dehydrogenase (IDH), and fumarate hydratase (FH) have been shown to be linked to specific alterations in metabolic activity in cancer cells (11, –, 14)." (PMID 26023239, 2015). "Janku, one of the colleagues, further implied urinary cfDNA might have utility in detecting advanced cancer patients with BRAF-mutant tumors for treatment response." (PMID 26448936, 2015). "CIMP high was strongly prevalent in the BRAF mutant/MSI cancers (at 86%), therefore this was evident in the BRAF mutant/MSS cohort (61% CIMP high rate) where CIMP high was more frequent in PRDM5 methylated compared to unmethylated cancers (27/36, 75.0% vs 27/53 50.9%; p = 0.03)." (PMID 25613750, 2015). "EGFR inhibitors, MEK inhibitors, and BRAF inhibitors can control the growth of cancer cells by abating extra pathway activity, so effects of these drugs partially depend on their ability to control aberrant activity of the pathway due to activating oncogene mutations." (PMID 26220863, 2015). "Furthermore, the largest effect is observed in lipid droplets of cancer cells harbouring wild-type BRAF and KRAS that were treated with erlotinib." (PMID 26168967, 2015). "Moreover, we re-sequenced five exons from three frequently-mutated cancer genes, AKT1, PIK3CA, and BRAF, in an additional 120 ESCC samples." (PMID 26386145, 2015). "Moreover, alternate pathways through mutation in BRAF and KRAS genes are associated with the progression of polyps to cancer." (PMID 25932044, 2015). "In our study, we demonstrated that using the BEAMing technology, testing for 21 oncogenic mutations in BRAF, EGFR, KRAS and PIK3CA genes in the plasma cfDNA of patients with advanced cancers referred for treatment with experimental targeted therapies, is feasible." (PMID 25980577, 2015). "We developed a novel mass spectrometry multiplexed genotyping platform named PentaPanel to concurrently assess single nucleotide polymorphisms in 56 hotspots of the 5 most clinically relevant cancer genes, KRAS, NRAS, BRAF, EGFR and PIK3CA for a total of 221 detectable mutations." (PMID 26435479, 2015). "The relationship between BRAF mutation and cancer relapse in mainly low-stage PTC population is not significant." (PMID 26177218, 2015). "However, of the 30 cases that were classified as BSRTC I-III but proved to be carcinomas by histopathology, 27 were positive for BRAFV600E mutation, indicating the vital value of BRAF mutation analysis in lesions with BSRTC I-III." (PMID 26597052, 2015).
cancer (continued). "BRAF mutations have also been associated with poor survival, but this phenomenon is restricted to carcinomas not showing microsatellite instability." (PMID 26299805, 2015). "In silico predictions indicated that a metastatic suppressor gene such as KLF17 and two cellular protein, RBM10 and TOX3 which are involved in proliferation and apoptosis of cancer cells could be the actors influencing the outcome of BRAF inhibitor therapy." (PMID 25437182, 2014). "The BRAF V600E mutation is present in approximately 10–15% of sporadic colorectal cancer (CRC) and is a hallmark of the serrated neoplastic pathway of CRC, where cancers develop from serrated precursor polyps." (PMID 24651849, 2014). "One consideration is increasing evidence that molecular aberrations often do not segregate by histetology; for instance, BRAF mutations can be found in a subset of patients with almost any cancer." (PMID 25593991, 2014). "BRAF wild type cancers are typically MSS and display chromosomal instability (CIN)." (PMID 24651849, 2014). "A number of BRAF mutants other than V600 were identified in human cancers." (PMID 24743024, 2014). "However, no information is available from the literature regarding the status of BRAF or PIK3CA in this cancer type." (PMID 24642661, 2014). "BRAF mutant/MSS (BRAFmut/MSS) cancers (n = 33) and BRAF mutant/MSI (BRAFmut/MSI) cancers (n = 30) were compared for presence of copy number aberrations (CNAs) indicative of CIN, with BRAF wild type/MSS (BRAFwt/MSS) cancers (n = 18) using Illumina CytoSNP-12 arrays." (PMID 24651849, 2014). "In the responsive group, 9 mutations (26%) were found in genes concerning proliferation pathways: PIK3CA (2 ADC with exon 9 E545K, and a poorly differentiated carcinoma with H1047R), BRAF (V600E in 2 ADC), STK11 (V197fs 69 in one ADC and F354L in one SCC), NTRK2 (L755L in a SCC) and MET (N375S)." (PMID 25561229, 2014). "We were also interested in evaluating NFE2L2 mRNA expression in relation to BRAF and KRAS mutations, since mutations to these genes occur frequently in PTC, and mutated KRAS and BRAF are associated with increased transcription of NFE2L2 in other cancers." (PMID 24138990, 2013). "While CCND2, a cell cycle regulator, VEGFA, an essential regulator of angiogenesis in a variety of cancer types and BRAF, an oncogene in a variety of cancers, most likely serve as our “proof of concept” genes for demonstrating functional significance in human ERMS." (PMID 24009521, 2013). "The BRAF mutant subset alone has a higher incidence than many other human cancers." (PMID 23845441, 2013). "Following BRAF activation, Csf-1 is markedly overexpressed in the murine cancers." (PMID 23372702, 2013). "High level microsatellite instability (MSI-H) occurs in 50% of human BRAF mutant cancers." (PMID 23845441, 2013). "Taken together with previous reports on BRAF and CIMP, we hypothesize that Cdx2 loss may play an early role in the progression of cancers arising through the serrated pathway." (PMID 24130965, 2013). "Thus, analysis of the distribution of BRAF aids in understanding the origins of multifocal carcinomas." (PMID 23599804, 2013). "Therefore, simultaneous study of other factors involved in BRAF network is crucial for a better understanding of its role in cancer." (PMID 23056577, 2012). "BRAF plays a very important role in cancer initiation and progression." (PMID 23056577, 2012). "Both methods found similarly high frequencies of CIN occurring in MSS cancers regardless of BRAF mutation status." (PMID 23110075, 2012). "This suggests that Aurora kinase family members, particularly AURKB, may play a role in mediating CIN in advanced BRAF mutant/MSS cancers." (PMID 23110075, 2012).
cancer (continued). "The extensive degree of CIN found in BRAF wild type/MSS cancers has been well documented." (PMID 23110075, 2012). "This may imply that CIN at certain genomic regions contributes to the worse survival of BRAF mutant/MSS cancers." (PMID 23110075, 2012). "A low level of CIN has been found in CIMP positive cancers using a genome wide array approach, however BRAF mutational status was not assessed." (PMID 23110075, 2012). "Also, there are trials with single-agent MEK162 or AZD6244, both MEK inhibitors in BRAF mutant cancers." (PMID 22792460, 2012). "As BRAF mutant cancers are thought to derive from a serrated polyp, and BRAF mutant cancers that are microsatellite unstable are diploid; it may be postulated that BRAF mutant/MSS cancers would also be CIN-negative." (PMID 23110075, 2012). "It is well established that BRAF mutant cancers predominantly occur in the proximal colon." (PMID 23110075, 2012). "Additionally, in BRAF mutant/MSS cancers there was a greater rate of co-occurrence of CIMP and CIN in late compared to early stages (63% and 31% respectively)." (PMID 23110075, 2012). "This may suggest that the compounding effects of both chromosomal and epigenetic instabilities could contribute to the aggressive phenotype and unfavourable outcomes observed in patients with a BRAF mutant/MSS cancer." (PMID 23110075, 2012). "However, constitutive activating mutations in signaling components downstream of EGFR, like NRAS(Q61L) or BRAF(V600E), are common in cancer cells." (PMID 22253908, 2012). "Furthermore, clinicopathological data between the BRAF mutant/MSS cancers and BRAF wild type/MSS cancers, also correlated in terms of a more advanced stage of presentation, comparable ages of onset, and equal gender distribution." (PMID 23110075, 2012). "It is tempting to speculate, that a PAK1-like function is critical to these cancers, but in Ras-mutated cells the signal to PAK1 originates directly from Ras, while BRAF needs a cooperating event to achieve the same goal." (PMID 22869096, 2012). "Interestingly, this study clearly demonstrates a high frequency of CIN and CIMP co-occurrence in the BRAF mutant/MSS cancers (72%), which suggests these forms of genetic and epigenetic instabilities can coexist within this molecular background." (PMID 23110075, 2012). "CIN in BRAF mutant/MSS cancers correlated with advanced stage (AJCC III/IV: 15/17, 88%; p = 0.02); showed high rates of co-occurrence with the CpG Island Methylator Phenotype (17/23, 74%); and CIN at 18q and 8p associated with worse survival (p = 0.02, p<0.05)." (PMID 23110075, 2012). "There is an ongoing trial of the BRAF inhibitor, PLX3603, in BRAF mutant cancers." (PMID 22792460, 2012). "Methylation of the individual genes was more common among proximal, MSI-high, and BRAF mutated cancers, although not statistically significant for all comparisons." (PMID 21777459, 2011). "Overall, we found a higher frequency of women and younger patients with cancer harboring BRAF mutation compared to those without the mutation." (PMID 22039425, 2011). "In some cancer settings, PTEN and BRAF mutations appear to interact." (PMID 21422497, 2011). "BRAF-V600E-mutated cell lines are solely dependent on RAF/MEK/ERK signaling for survival and this oncogene addiction makes RAF/MEK inhibitors relevant compounds for treatment of cancer." (PMID 21853067, 2011). "The higher frequency of KRAS mutations was clearly more evident (although not statistically significant) in cancers with a residual serrated adenoma (57.1%, 16/28), being observed twice as often as BRAF mutations (28.6%, 8/28)." (PMID 21457162, 2011).
cancer (continued). "The importance of this finding is further emphasized by the fact that pharmacologic MEK pathway inhibition of cell proliferation in BRAF mutant cancers may be significantly decreased by the presence of activating PIK3CA mutations." (PMID 21738740, 2011). "In the present study, however, BRAF mutation rate was only 12.2% for MSI-high CRCs, which was consistent with a previous report for patients of the same ethnic background (10.5% among MSI-high carcinomas)." (PMID 21827707, 2011). "BRAF mutations were found more frequently in CIMP-high (26.5%) than in CIMP-low/negative carcinomas (0.9%)." (PMID 21827707, 2011). "NRAS and BRAF mutations are mutually exclusive, such that they are not both found mutated in the same cancers, suggesting that activation of either BRAF or RAS is sufficient for pathological activation of the MAPK pathway." (PMID 20230482, 2010). "This raises the possibility that KRAS and BRAF mutant cancer cells might be differentially dependent on signalling mechanisms that involve MEK." (PMID 19018267, 2008). "In cancer, the majority of somatic BRAF mutations result in missense substitutions found in, but not limited to, exon 11 (the glycine-rich loop) and exon 15 (the activation segment) in the protein kinase domain." (PMID 18060073, 2007). "In addition, we performed targeted-panel sequencing covering the coding sequences of 410 cancer-associated target genes exemplarily on Mel-DCC-11 (parental, sensitive to BRAF inhibitor) and its Vemurafenib-resistant derivative Mel-DCC-11-R) to identify resistance-causing mutations." (PMID 41350774, 2026). "Since studies have indicated that combinations of different classes of RAF inhibitors could be synergistic in both RAF WT and BRAF V600E cancer cells, we also compared the efficacy of combining type 2 RAFi with type 1 RAFi (dabrafenib and vemurafenib) or with MEKi." (PMID 41023593, 2025). "BRAF V600E mutation results in an elevation in BRAF kinase activity, spanning from 130 to 700 times that of the wild-type, leading to prolonged aberrant activation of the Mitogen-activated Protein Kinase (MAPK) pathway and driving the initiation and progression of cancer." (PMID 40868288, 2025). "BRAF mutations are independent of tissue origin and may provide additional opportunities for therapeutic strategies in patients with different cancers, especially those with rare cancers." (PMID 41160271, 2025). "Due to the rarity of this alteration, the combination of the BRAF inhibitor dabrafenib and the MEK inhibitor trametinib was evaluated in the Rare Oncology Agnostic Research (ROAR) trial, a basket study investigating dabrafenib plus trametinib in BRAF V600E-mutated rare cancers." (PMID 40585845, 2025). "Our data suggest, however, that this benefit may be reduced, or absent, for cancers carrying both atypical BRAF and additional Ras mutations." (PMID 39751654, 2025). "Thus, atypical BRAF mutations do not seem to follow the serrated/MSI/CIMP/RNF43 pathway of colorectal tumorigenesis but instead resemble cancers following the canonical pathway of colorectal tumorigenesis." (PMID 39751654, 2025). "The immunomodulatory effects of HDAC inhibitors suppressing immune evasion by BRAF-mutant tumors appear to be especially promising, given a growing number of immune therapeutics such as checkpoint inhibitors that have been approved for cancer therapy over the last few years." (PMID 39935431, 2025). "previously demonstrated cellular movement/cancer/cellular response to therapeutics and cell death and survival/cell–cell signalling and interaction/cellular growth and proliferation as the key resistance pathways specific to BRAF resistance in A375 and SK‐MEL‐2 cell lines." (PMID 40135438, 2025).